WEE1 (WEE1 G2 checkpoint kinase)
Diseases named in the same sentence as WEE1 in open-access papers (continued):
Sharing a sentence is not in itself a finding about the gene and the disease.
endometriosis (7 papers, 2017 to 2023). The growth of functional endometrial tissue in anatomic sites outside the uterine body. "Future studies should further examine the effects of WEE1 inhibitors on the progression of endometriosis in patients susceptible to this disease." (PMID 34686198, 2021). "We found that treatment with the inflammatory cytokine, interleukin-1β (IL-1β) induced WEE1 expression in ESCs, indicating that upregulation of WEE1 may be associated with the inflammatory response during endometriosis." (PMID 34686198, 2021). "Since the Wnt/β-catenin signaling pathway has been implicated in the pathophysiology of endometriosis, we next examined whether WEE1 exerts its fibrosis-inducing effects in ESCs via the β-catenin signaling pathway." (PMID 34686198, 2021). "Thus, we hypothesized that the upregulation of WEE1 observed in endometriosis patients may be associated with the endometriosis-induced inflammatory response." (PMID 34686198, 2021). "In the same study, looking at 32 MII-stage oocytes from healthy versus woman with endometriosis, it was found that WEE1 was upregulated in the latter group." (PMID 37558907, 2023). "In a mouse model of endometriosis, the WEE1 inhibitor AZD1775 significantly reduced fibrosis in ectopic and eutopic tissues." (PMID 34686198, 2021). "Taken together, our results demonstrated that WEE1 expression is significantly upregulated in a mouse model of endometriosis, and that inhibition of WEE1 can prevent the development of endometriosis-induced endometrial fibrosis in mice." (PMID 34686198, 2021). "To examine the role of WEE1 during the development of endometriosis, we first sought to determine the effects of WEE1 overexpression or knockdown on the migration of ESCs in vitro." (PMID 34686198, 2021). "Prior to induction of endometriosis, mice were treated with either Estradiol (100 μg/kg/week), the WEE1 inhibitor, AZD1775 (40 mg/kg/day) or Estradiol+AZD1775." (PMID 34686198, 2021). "Using western blotting to examine the eutopic and ectopic endometrium of the endometriosis mouse model, we found significantly increased WEE1 expression in the eutopic and ectopic endometrium compared to the endometrium of normal mice." (PMID 34686198, 2021). "We next sought to determine whether the fibrosis-promoting effects of WEE1 observed in vitro in ESCs also occurred in vivo in our mouse model of endometriosis." (PMID 34686198, 2021). "Our preliminary data indicate that upregulation of WEE1 as part of the endometriosis-induced inflammatory response may lead to increased fibrosis." (PMID 34686198, 2021). "Since WEE1 inhibitors have already been used in the treatment of cancers, we propose that these inhibitors could be applied to patients with endometriosis." (PMID 34686198, 2021). "Our study describes a role for WEE1 in the pathogenesis of endometriosis." (PMID 34686198, 2021). "Our hypothesis was subsequently validated in a mouse model of endometriosis, confirming that WEE1 appears to be involved in the pathogenesis of endometriosis." (PMID 34686198, 2021). "Since clinically applicable inhibitors of WEE1 have previously been used to treat cancer, we propose that their clinical application could be extended to the treatment of endometriosis." (PMID 34686198, 2021). "Our findings indicate that WEE1 may be a potential therapeutic target in the treatment of endometriosis." (PMID 34686198, 2021). "Interleukin-1β (IL-1β) induced WEE1 expression in endometrial stromal cells (ESCs), suggesting that WEE1 may be upregulated during the endometriosis-induced inflammatory response." (PMID 34686198, 2021). "Although WEE1 was recently identified as a differentially upregulated gene in the oocytes of ovarian endometriosis patients, virtually nothing is known about its role in the pathogenesis of endometriosis." (PMID 34686198, 2021).
endometriosis (continued). "Here, we found that overexpression of WEE1 led to increased expression of the fibrotic markers, α-SMA and Collagen I, in both ESCs as well as in our mouse model of endometriosis, suggesting that WEE1 may also have a role in mediating fibrosis." (PMID 34686198, 2021). "Since endometriosis is accompanied by inflammation in humans, our results suggest that WEE1 expression levels may be due to the endometriosis-induced inflammatory response." (PMID 34686198, 2021). "Studies have shown that WEE1 is significantly upregulated in oocytes of endometriosis patients." (PMID 34686198, 2021). "Here, we sought to determine whether WEE1 has a role in the development of endometriosis." (PMID 34686198, 2021). "Furthermore, since treatment with IL-1β increased WEE1 expression levels in ESCs, modulation of WEE1 in response to inflammatory signals may provide an additional strategy for limiting fibrosis during endometriosis." (PMID 34686198, 2021). "Thus, WEE1 may serve as a potential therapeutic target for the treatment of endometriosis." (PMID 34686198, 2021). "Among the top 20 genes, APOE, DUSP1, MGST1, G0S2, ID4, WEE1, and H2AFZ expression levels were upregulated in the oocytes of patients with endometriosis." (PMID 33467661, 2021). "Together, these findings indicate that WEE1 is involved in ESC migration and survival, and may therefore have a role in the development of endometriosis." (PMID 34686198, 2021).
Ewing sarcoma (7 papers, 2022 to 2026). A small round cell tumor that lacks morphologic, immunohistochemical, and electron microscopic evidence of neuroectodermal differentiation. "Taken together, these results demonstrate that the combined inhibition of DDK and WEE1 causes premature mitotic entry, mitotic progression abnormalities and ultimately mitotic catastrophe in Ewing sarcoma cells." (PMID 36338546, 2022). "In this study, we identify that HDAC inhibitors more broadly disrupt DNA replication and the cellular response to DNA replication stress by downregulating the expression of RRM1, RRM2, CHK1, and WEE1 in Ewing sarcoma cells." (PMID 40478628, 2025). "Our findings show that combined inhibition of RNR and WEE1 was effective against Ewing’s sarcoma in vitro." (PMID 39962391, 2025). "They thus provide a rationale for the evaluation of the potential of combined targeting of RNR and WEE1 in Ewing’s sarcoma in vivo." (PMID 39962391, 2025). "In this study, we identified that multiple HDAC inhibitors, including fimepinostat, romidepsin, and panobinostat, downregulate the levels of the RRM1, RRM2, CHK1, and WEE1 proteins in Ewing sarcoma cells and impair DNA replication." (PMID 40478628, 2025). "In this study, the combined targeting of ribonucleotide reductase (RNR) and WEE1 was explored for its effectiveness against Ewing’s sarcoma cells." (PMID 39962391, 2025). "Specifically, the addition of a WEE1 inhibitor forces DDKi-treated Ewing sarcoma cells into mitosis prematurely." (PMID 36338546, 2022). "This suggests that, upon DDK inhibition, WEE1 activity prevents further cell cycle progression, limiting DDKi-induced mitotic aberrations in Ewing sarcoma cells." (PMID 35220396, 2022). "Together, these results suggest that mitotic progression is required to elicit the cytotoxic effects induced upon combination treatment with DDK and WEE1 inhibitors in Ewing sarcoma." (PMID 36338546, 2022). "Here, we have discovered that the inhibition of WEE1 can be used to enhance the sensitivity of Ewing sarcoma cells to DDKis." (PMID 36338546, 2022). "Importantly, we have found that DDK and WEE1 inhibitors display a synergistic relationship with regards to reducing cell viability of Ewing sarcoma cells." (PMID 36338546, 2022). "However, the decision to focus on the inhibition of WEE1 to overcome the DDKi-induced mitotic entry delay in Ewing sarcoma was based on the following three things." (PMID 36338546, 2022). "This is the first study to utilize the inhibition of DDK in combination with WEE1, offering a unique therapeutic combination that may prove efficacious for Ewing sarcoma as well as a variety of other tumor types that have a similar sensitivity to DDKis." (PMID 36338546, 2022). "In this work, we identify that HDAC inhibitors broadly disrupt DNA replication and the response to replication stress in Ewing sarcoma cells by downregulating RRM1, RRM2, CHK1, and WEE1." (PMID 40478628, 2025). "Treatment of Ewing sarcoma cell lines with DDK inhibitors reduced the rate of DNA replication, prolonged the S-phase, induced aberrant mitotic progression, and demonstrated synergy with WEE1 inhibitors." (PMID 40478628, 2025). "The Wee1 inhibitor MK1775/AZD1775 has been and/or is currently being tested in dozens of human tumors (clinicaltrials.gov), though not in Ewing sarcoma to date." (PMID 36338546, 2022). "In contrast, we did not observe a decrease in the viability of A673 (Ewing sarcoma [ES], EWSR1-FLI1+) or RH41 (alveolar rhabdomyosarcoma, PAX3-FOXO1+) cells upon WEE1 KD compared with control." (PMID 35315355, 2022).
serous ovarian cancer (7 papers, 2022 to 2026). "A recent study suggest higher copy number of CCNE1 predicts higher sensitivities of high grade serous ovarian cancer to combination of WEE1 and ATR1." (PMID 37087441, 2023). "In addition, the EFFORT study assessed the addition of olaparib to the Wee1 inhibitor adavosertib in PARPi-resistant high-grade serous ovarian cancer with some success and manageable adverse effects." (PMID 41520277, 2026).
acute leukemia (5 papers, 2018 to 2023). A clonal (malignant) hematopoietic disorder with an acute onset, affecting the bone marrow and the peripheral blood. "This study aimed to analyze the pharmacodynamic synergy between the anti-metabolite cytarabine and WEE1 inhibitor adavosertib on acute leukemia cell lines CCRF-CEM and Jurkat." (PMID 37633054, 2023). "As resistance to kinase inhibitors is frequent, we sought to identify mechanisms of resistance to WEE1 inhibition in acute leukemia." (PMID 32195191, 2020). "Recently, the potential synergistic effects of combining WEE1 and PARP1 inhibition in acute leukemia revealed also a potential synergistic effect, creating a double-hit model by increasing DNA damage and preventing DNA damage repair." (PMID 29489886, 2018).
esophageal cancer (5 papers, 2007 to 2025). A primary or metastatic malignant neoplasm involving the esophagus. "Wee1 inhibition has been shown to radiosensitize cells of different cancer entities, such as head and neck squamous cell carcinoma, esophageal cancer and GBM cells." (PMID 36709315, 2023). "Wee1 inhibition is a promising approach to sensitize various tumor entities towards irradiation since it has been shown to be effective in different cancer cell types such as hepatocellular, head and neck and esophageal cancer." (PMID 36709315, 2023).
mantle cell lymphoma (5 papers, 2015 to 2022). Mantle cell lymphoma is a rare form of malignant non-Hodgkin lymphoma affecting B lymphocytes in the lymph nodes in a region called the ``mantle zone''. "Particularly, MK-1775 enhances the efficacy of SRC inhibitors in BL, and the combination of CHK1 and WEE-1 inhibitors is synergistic in mantle cell lymphoma." (PMID 31836849, 2020). "Targeting WEE1 with AZD1775 in combination with the CHK1 inhibitor PF-00477736 resulted in cell killing and destabilization of the oncogenic transcription factor MYC in DLBCL and was strongly synergistic in mantle cell lymphoma." (PMID 29489886, 2018).
metastatic melanoma (5 papers, 2012 to 2023). A melanoma that has spread from its primary site to another anatomic site. "Since expression of Wee1 increased in direction from nevi to primary- and metastatic melanomas, we next examined the relationship between Wee1 expression, clinical parameters and disease outcome." (PMID 22719872, 2012).
renal carcinoma (5 papers, 2015 to 2025). A carcinoma arising from the epithelium of the renal parenchyma or the renal pelvis. "For instance, miR-381 was found to target WEE1, thereby regulating cell proliferation in renal cancer cells." (PMID 26688820, 2015).
uterine serous carcinoma (5 papers, 2022 to 2025). "The WEE1 inhibitor ZN-c3 has been granted fast track designation by the FDA for treatment of patients with uterine serous carcinoma and is included in nine other clinical trials testing its efficacy in various other types of cancer." (PMID 36276148, 2022). "In addition, recent ADAGIO phase 2 trial results of the Wee1 inhibitor adavosertib (AZD1775) demonstrating response rates of 30% in uterine serous carcinoma are promising and warrant further investigation." (PMID 36835335, 2023). "One WEE1 inhibitor, ZN-c3, has been granted fast track designation by the FDA for treatment of patients with uterine serous carcinoma." (PMID 36276148, 2022). "Given the molecular similarities between uterine serous carcinomas and UCS, we hypothesized that Wee1-directed therapy may also be active in UCS." (PMID 40678577, 2025).
anemia (4 papers, 2013 to 2025). A reduction in the number of red blood cells, the amount of hemoglobin, and/or the volume of packed red blood cells. "From the GSE4619 data, WEE1 gene expression was unchanged, according to the MDS staging (by the French American British classification), from refractory anemia to refractory anemia with excess blasts (RAEB)." (PMID 37370065, 2023).
B-cell lymphomas (4 papers, 2015 to 2024). "Bortezomib reduced the WEE1 expression of B-cell lymphoma cell lines, while another study found that bortezomib increased the expression level of WEE1 in vascular endothelial cells." (PMID 37834095, 2023). "The effects of a Chk1 inhibitor (PF-00477736) and a Wee1 inhibitor (MK-1775) have been herein investigated in a large panel of mature B-cell lymphoma cell lines." (PMID 25428911, 2015). "Here, we have explored the effects of Chk1 and Wee1 inhibitors as single agents in a wide panel of B-cell lymphomas." (PMID 25428911, 2015). "We herein performed a cytotoxic screening in 35 B-cell lymphoma cell lines with Chk1 and Wee1 inhibitors." (PMID 25428911, 2015). "Chk1 inhibitors have been shown to be effective against mouse models Myc-driven malignancies, such as B-cell lymphoma, and Wee1 inhibitors enhance the efficacy of the SRC inhibitors in Burkitt lymphomas." (PMID 25428911, 2015).
colon adenocarcinoma (4 papers, 2015 to 2025).
glaucoma (4 papers, 2015 to 2025). Increased pressure in the eyeball due to obstruction of the outflow of aqueous humor. "WEE1, SMC2, HMGB1, RRM2, and POLA1 proteins were also observed to be involved in the progression and invasion of retinoblastoma; SLC24A2 and DTX4 in age-related macular degeneration; and EPHB6, EFNB3, and SHC1 in glaucoma." (PMID 34646884, 2021).
Infertility (4 papers, 2014 to 2022). "They discovered that of these four mutated essential meiosis genes, only a cyclin-dependent kinase 2 (Cdk2) allele mimicking SNP rs3087335, which alters an inhibitory WEE1 protein kinase phosphorylation site, caused infertility." (PMID 33562517, 2021). "Accordingly, cdk-1 (RNAi) suppresses wee-1.3 (RNAi) infertility and therefore serves as a positive control in these studies." (PMID 36060813, 2022). "Therefore, we systematically screened each of the 19S RP subunits to determine if there are additional subunits whose depletion suppresses wee-1.3 (RNAi) induced infertility." (PMID 36060813, 2022). "The mechanism by which the suppression of wee-1.3 (RNAi) infertility occurs is still unknown but future studies may offer new insights into the regulation of this highly conserved WEE-1.3/Myt1 cell cycle kinase." (PMID 36060813, 2022). "The premature expression of CBD-1::mCherry in WEE-1.3–depleted oocytes provides the first indication regarding why those oocytes might be fertilization-incompetent and wee-1.3(RNAi) results in infertility." (PMID 25298536, 2014). "Preliminary data indicate that some, but not all, mutants can suppress the wee-1.3(RNAi) infertility to a level similar to that observed upon RNAi depletion of the candidate (data not shown)." (PMID 25298536, 2014). "However, our previous study also reported that chemical inhibition of the proteolytic activity of the proteasome with bortezomib neither suppressed wee-1.3 (RNAi) infertility nor induced nuclear accumulation of WEE-1.3." (PMID 36060813, 2022). "In addition, we performed dilution analysis of the effectiveness of co-diluted wee-1.3(RNAi) with a control RNAi that does not affect fertility (smd-1), and we found that diluting wee-1.3 by five-fold does not alter the observed infertility phenotype (data not shown)." (PMID 25298536, 2014).
laryngeal squamous cell carcinoma (4 papers, 2017 to 2024). A squamous cell carcinoma that arises from the larynx. "WEE1 is a protein kinase that regulates the G2 checkpoint and prevents entry into mitosis in response to DNA damage and is frequently overexpressed in various tumors, including laryngeal squamous cell carcinoma." (PMID 38540309, 2024). "However, the expression and clinical significance of WEE1 in human laryngeal squamous cell carcinoma (LSCC) are still unknown." (PMID 30323762, 2018).
lymph node metastasis (4 papers, 2013 to 2020). "In this study, we reported that WEE1 was significantly expressed in LSCC tissues than adjacent normal tissues, and the expression level of WEE1 was associated with T stage, lymph node metastasis and poor survival of patients with LSCC." (PMID 30323762, 2018). "Wee1 kinase is increased in vulvar squamous cell carcinomas, as compared to expression in normal epithelium, and a high Wee1 expression is associated with markers of malignancy, such as lymph node metastasis and poor differentiation." (PMID 23767999, 2013). "In conclusion, the association between high Wee1 expression and presence of lymph node metastasis and poor tumor differentiation suggest that Wee1 may be involved in the progression of vulvar carcinomas." (PMID 23767999, 2013). "High expression of Wee1 in the nucleus was significantly correlated with younger age (P = 0.01) and presence of lymph node metastasis (P = 0.04)." (PMID 23767999, 2013). "Importantly, overexpression of WEE1 was correlated with T stages, lymph node metastasis, clinical stages and poor prognosis of LSCC patients." (PMID 30323762, 2018). "The expression of WEE1 protein in T1-2, negative lymph node metastasis and stage I+II groups were respectively lower than that in T3-4, positive lymph node metastasis and stage III+IV groups." (PMID 30323762, 2018). "Lymph node metastasis stage 0 and stage 1-3 did not significantly correlate with WEE1 expression." (PMID 27363019, 2016). "However, the association between high Wee1 expression and the presence of lymph node metastasis as well as poor tumor differentiation found in vulvar cancers does not immediately support the tumor suppressor role of Wee1." (PMID 23767999, 2013).